AGO2 (argonaute RISC catalytic component 2)
Diseases named in the same sentence as AGO2 in open-access papers (continued):
Sharing a sentence is not in itself a finding about the gene and the disease.
infection (continued). "Similarly, knockdown or inactivation of Dicer-2 and Ago2 in mosquitoes results in higher viral titers upon infection with different viruses." (PMID 31100912, 2019). "However, although a transcript upregulation of both dcr2 and ago2 was observed upon infection, the observed effect was very moderate." (PMID 29403066, 2018). "Next, we tested whether the endogenous siRNAi components, namely T. ni Dcr2 and Ago2, are differentially regulated in High Five cells upon infection with CrPV." (PMID 29403066, 2018). "Furthermore, silencing of AGO2 in Lutzomyia cells leads to increased viral replication, which suggests they fail to control infection." (PMID 29864168, 2018). "We show that RVFV cannot be targeted by artificially induced siRNAs only and that infection produces virus-derived small RNAs with antiviral activity, that Ago2, Piwi4, and Ago3 are involved in the antiviral response, and that RVFV is unable to inhibit at least dsRNA-induced RNAi." (PMID 28497117, 2017). "mdm-miR403a and AGO2 showed a similar expression trend during the Vm infection." (PMID 29270184, 2017). "Moreover, EMCV infection of mESCs resulted in Dicer-dependent accumulation of ∼22-nt vsiRNAs that are incorporated into AGO2, which was lost upon differentiation." (PMID 28815217, 2017). "It is also possible that other AGOs including AGO2 localize to PGs and regulate infection." (PMID 26641460, 2015). "On days 10 and 12 post infection, the infectious virus titers in feeding solutions from at least one of the mosquito groups with impaired RNAi (dsRNA.dcr2-, dsRNA.ago2-, and dsRNA.r2d2-injected) were higher (P<0.05) than in control groups (dsRNA.βGAL-injected, PBS-injected, and non-injected)." (PMID 19214215, 2009). "The average titer for mosquitoes injected with dsRNA.dcr2 was >10-fold higher than the average titer of control dsRNA-treated mosquitoes and a small but significant number of dsRNA.dcr2- and dsRNA.ago2-injected mosquitoes had virus titers 100-fold higher than in control infections." (PMID 19214215, 2009). "In addition, in a transgenic Ae. aegypti line, Ago2 is required for RNAi-mediated defense against Dengue virus (family Flaviviridae; genus Flavivirus) infection." (PMID 18366655, 2008). "Therefore, the modulation of miR-184 in the saliva of the CHIKV-infected mosquitos may alter the host immune response by modulating Ago2 at the site of infection." (PMID 36851776, 2023). "Our results now show that Ago2 disruption in adult mosquitoes significantly represses autophagy and enhances mosquito death most likely because the cells fail to clear the damaged organelles and other cytoplasmic components that are produced by hyper-infection with arboviruses." (PMID 37723154, 2023). "Besides disrupting CrPV-1A’s ability to block SG assembly and Ago-2 activity, the CrPV-1A protein localizes to the nuclear periphery and mediates poly (A)+ mRNA nuclear enrichment and global transcriptome changes under infection." (PMID 36455064, 2022). "Moreover, an up-regulation of AGO2 expression after infection was reported in Arabidopsis after infection by the biotrophic bacteria P. syringae, in the oil crop B. napus infected by the fungal necrotrophic Sclerotinia sclerotiorum, and in the cowpea Vigna unguiculata infected by CPSMV." (PMID 35052407, 2021). "A broader study including other model viruses from several Baltimore classes should shed light on whether the absence of changes in transcript expression levels, and mainly of induction of Dcr-2 and Ago-2 proteins, is a general response against infections with natural viruses in D. melanogaster." (PMID 32194567, 2020). "To discern whether the reduced virus abundance in heat-shocked honey bees was due to higher expression of honey bee immune genes, we assessed the relative expression of three honey bee antiviral defense genes (i.e., mf116383, dcr-like, and ago2) at 72 h post-infection." (PMID 32098425, 2020).
infection (continued). "However, we were unable to detect any effect of AGO2 silencing on the infections rates, probably due to a limited reduction on AGO2 expression or simply by the fact that we used a high concentration of MAYV in the blood meal." (PMID 32784948, 2020). "Since overexpression of Dcr2 and Ago2 led to an enhanced antiviral response, we wondered whether upregulation of these key siRNAi components could constitute a natural cellular response upon an acute infection of CrPV." (PMID 29403066, 2018). "To explore the molecular basis of the AGO2 suppression of RIG-I signaling, we first examined the interaction between RIG-I and AGO2 under different infection conditions in A549 cells." (PMID 40949099, 2025). "To assess the effect of SFTSV on the functional activity of the RNAi pathway, we first confirmed the interaction between endogenous host AGO2 and SFTSV NSs under infection condition." (PMID 40013801, 2025). "While infection with the UK3 strain of PVX induced mosaic symptoms in tomato plants, systemic necrosis occurred when AGO2 was silenced." (PMID 38996815, 2024). "A significant increase in mRNA levels of AGO2, DICER1, DGCR8, and XPO (all p-values= 0.03) was found 24 h after infection." (PMID 37243263, 2023). "In this study, we constructed RNAi component mutants for each of DCL1, DCL2, AGO1, AGO2, RDRP1, RDRP2, and RDRP3, and analyzed sRNA profiles in A. flavus to explore the role of each RNAi component in AfPV1 infection of A. flavus." (PMID 38033556, 2023). "Here we show that infection with the Turnip yellow mosaic virus (TYMV) is enhanced in Arabidopsis ago1, ago2 and dcl4 mutants, which are impaired in the execution of PTGS, but not in dcl2, rdr1 and rdr6 mutants, which are impaired in the amplification of PTGS." (PMID 36696453, 2023). "For example, infection with Rosellinia necatrix mycovirus 3 (RnMyRv3) or Rosellinia necatrix megabirnavirus 1 (RnMBV1) upregulates the expression of genes DCL2, AGO2, RDRP1, and RDRP2 in R. necatrix." (PMID 38033556, 2023). "In contrast, inhibition of Ago2 in THP-1 cells prior to infection using BCI-137 significantly reduced intracellular replication of L. pneumophila, again indicating that a functioning Ago2 is necessary for its optimal proliferation." (PMID 35140216, 2022). "The necrotic symptoms observed in the PVX-infected hpAGO2.3 plants suggest that AGO2, AGO3 or both are also distinctly involved in tolerance to infection with PVX." (PMID 33032637, 2020). "This is illustrated by AGO2, CABBP1, and NBR1 genes, which produce vasiRNAs upon infection likely to regulate the levels of their transcripts." (PMID 33230160, 2020). "During an infection, when AGO1 is targeted by viral silencing suppressors, AGO2 expression is upregulated." (PMID 33031436, 2020). "We found no obvious differences in the total accumulation levels of Dicer, AGO1, AGO2, PACT, or TRBP in 293T cells after infection with IAV-PR8, IAV-WSN, or Sendai virus." (PMID 33281788, 2020). "Correspondingly, 23% of the infection-induced fungal sRNAs started with C, binding preferentially to AGO5 in Arabidopsis, and 16.7% started with A, binding preferentially to AGO2 and AGO3 in Arabidopsis." (PMID 31969895, 2019). "Therefore, although these data do not allow to clearly conclude that an upregulation of dcr2 and ago2 constitutes an active cellular defense strategy in the case of a CrPV acute infection, it is possible to conclude that the RNAi-genes are differentially regulated during the infection." (PMID 29403066, 2018). "AGO2 and AGO5 restrict infection in leaves, while AGO1 and AGO10 protect inflorescence from systemic infection by TuMV." (PMID 29538326, 2018). "Despite the dramatically different outcome of infection, PVX genomic RNA (gRNA) levels were only slightly elevated in systemically infected leaves of the ago2 mutants compared to wild-type plants." (PMID 28432338, 2017). "Following infection with FHV, Ago2, dsRNA and CG4572, also localized along nanotube-like structures." (PMID 27255932, 2016).
infection (continued). "The authors expressed their concern in interpreting infection results for AGO1 due to the large number of genes that are deregulated when AGO1 is disrupted, including AGO2 induction." (PMID 26641460, 2015). "Expression of potyviral HC-Pro, infection with TCV, and infection with Pseudomonas syringae result in increased AGO2 expression; AGO2 regulates expression of MEMB12 and possibly other genes." (PMID 25806948, 2015). "In the current study, we intrathoracically injected HWE mosquitoes with dsRNA.dcr2, dsRNA.ago2 or dsRNA.r2d2 prior to DENV2 infection and showed reduced corresponding mRNA 2 days later, at the time of infection." (PMID 19214215, 2009). "Monitoring midgut Ago2, Dcr2, and TSN transcript levels during infection revealed that only TSN transcripts were significantly increased in midguts over blood-fed controls." (PMID 18366655, 2008). "As expected, increased levels of phosphorylation of IRF3 and STAT1 were found in AGO2 knockout cells after infection with DelNS1 WSN virus, regardless of the presence of DROSHA." (PMID 40949099, 2025). "We identified AGO2 to be a negative modulator of RIG-I-mediated antiviral signaling in responses to infection with RNA viruses." (PMID 40949099, 2025). "The tracks clearly showed no enrichment over background upon infection thus discounting a direct role of nuclear or cytoplasmic AGO2 in miRNA-mediated silencing of viral genes." (PMID 40219968, 2025). "To further investigate the mechanisms underlying the inhibition of apoptosis by circ-FGL1 during pathogen infection, we first assessed whether circ-FGL1 could be pulled down by the Argonaute 2 (AGO2) proteins." (PMID 39146353, 2024). "In C. parasitica, DCL2 and AGO2 were upregulated by CHV1 and mycoreovirus 1 (MyRV1) infections." (PMID 38033556, 2023). "Briefly, in the early stages of infection, when the viral RNA level is still low, predominantly DCL4 would produce limited amounts of 21 nt vsiRNAs, which would largely be used by the primary AGO—in this case AGO2—to limit the replication of the virus." (PMID 37603044, 2023). "However, in Vero E6 cells, AGO2, DICER1, DGCR8, and XPO5 mRNA levels were slightly upregulated 24 h after infection with SARS-CoV-2." (PMID 37243263, 2023). "More specifically, ZIKV replication was not significantly influenced by silencing Ago2, Piwi5 or Piwi6 irrespective of the type of infection." (PMID 37440582, 2023). "Given that Ago2 protein levels have been reported as modulated in conditions not evaluated here, such as infection procedure-related stress, status of targets of interest in additional stress should also be considered." (PMID 35172010, 2022). "Our findings are consistent with earlier studies which reported significant upregulation for multiple RNAi pathway‐related genes, including Argonaute‐2 (AGO2) and dicer‐like, in honey bees in response to acute infection with Israeli acute paralysis virus (IAPV)." (PMID 32985125, 2021). "Infection with DENV in Aedes aegypti induced the overexpression of Dicer2 and Ago2." (PMID 34452456, 2021). "For example, the ARGONAUTE 2 (AGO2) gene in A. thaliana limits PVX infection, but N. benthamiana AGO2 does not." (PMID 33889169, 2021). "Interestingly, we found obvious co-localization of NS1 and AGO2 in the cytoplasm and nucleus of 293T cells after IAV-WSN infection." (PMID 33281788, 2020).
infection (continued). "We analyzed the expression of transcripts and proteins for Dcr-2 and Ago-2 in three different fly strains infected with Drosophila C Virus (DCV) and Flock House Virus (FHV) by two different modes of delivery, injection and oral infection." (PMID 32194567, 2020). "After infecting different fly strains with two different viruses and modes of infection, we observed changes in Dcr-2 and Ago-2 protein concentrations that were not related with changes in gene expression." (PMID 32194567, 2020). "We did not observe any significant difference in Dcr-2 and Ago-2 mRNA levels of infected flies compared with mock infected flies, independent of the fly strain, virus or mode of infection used." (PMID 32194567, 2020). "Correlations between the number of various agranulocytes, granulocytes, and NK-lysin, dc1 and ago2 expressions in the peripheral blood of infection free cows (RID- and without inserted proviral DNA, Control group) in the cows of ZAO Mozhayskoe farm." (PMID 32582774, 2020). "(B) Percent cell confluence of HeyA8 CD95 k.o. cells transfected with either non-targeting siRNA (siCtr) or a pool of 4 siRNAs targeting AGO2 following subsequent infection with either empty pLenti (vec) or pLenti CD95L." (PMID 30324908, 2018). "In Arabidopsis, PVX failed to infect wild-type but not ago2 mutants, suggesting that AGO2 is required to suppress PVX infection." (PMID 29601523, 2018). "These experiments require the use of plants lacking AGO2-mediated antiviral functions, as infection by TuMV-AS9 would otherwise be blocked." (PMID 25806948, 2015). "Additionally, we show that the levels of crucial PB proteins (DDX6, AGO2 and TNRC6A) remain unchanged during infection." (PMID 21390246, 2011). "However, after infection with TCV, the AGO2 antibody detected two proteins of 113kDa (the predicted size of AGO2) and 108 kDa." (PMID 21305057, 2011). "MOI lower than 2 did not yield any nuclear translocation of AGO2 after 16 h of infection, suggesting that MOI < 2 may need longer time of infection." (PMID 40219968, 2025). "In hepatitis C virus (HCV) infection, for example, serum-derived exosomes were shown to carry replication-competent HCV RNA and assemble a complex of viral RNA with host factors (Ago2, miR-122, HSP90) that could infect naïve hepatocytes in a receptor-independent manner." (PMID 41012666, 2025). "Notably, we did not detect significant WNV-infection induced upregulation of canonical mosquito antiviral immune genes (e.g., AGO2, R2D2, etc.)at the whole-midgut level." (PMID 39869679, 2025). "Regardless of the infection, AGO2 was present in the P100 sample (lines 2 and 4) and depleted from S100 fractions (lines 1 and 3), confirming that it is in the same fraction as ribosomes, regardless of the infection." (PMID 39899642, 2025). "During infection, adenoviruses inhibit the cellular RNA interference (RNAi) machinery by saturating the RNA-induced silencing complex (RISC) of the host cells with large amounts of virus-derived microRNAs (mivaRNAs) that bind to the key component of the complex, Argonaute 2 (AGO2)." (PMID 38994969, 2024). "Thus, although the results are not statistically significant, our Ago2-CLIP indicated that RsmY seem to directly interact with Ago2 during infection." (PMID 35140216, 2022). "Therefore, the liberation of AGO2 mRNA from miR403-AGO1 mediated repression provided a plausible explanation for the strong induction of AGO2 mRNA and protein expression upon P1 infiltration and SPMMV infection (this study)." (PMID 33925878, 2021). "However, in some cases, an increase in virus replication was reported following Dcr2, but not Ago2, knockdown, in particular following infection with flaviviruses." (PMID 34205194, 2021). "We found that infection with H1N1 A/Texas/36/91 (TX 91) did not alter AGO2 subcellular redistribution (data not shown), which further narrowed down to the three non-conserved amino acids that might be responsible for the phenotype of IAV-WSN NS1." (PMID 33281788, 2020).
infection (continued). "Notably, no obvious changes in the subcellular accumulation of AGO1, AGO2, and PACT were observed in 293T cells after infection with the mutant of IAV-WSN deficient in the expression of NS1 (WSNΔNS1, lane 3)." (PMID 33281788, 2020). "From this point of view the pro-viral effect of AGO1 would be indirect because the higher AGO2 levels could explain the negative impact the silencing of AGO1 had on the infection." (PMID 33031436, 2020). "In our previous study, we applied RNA-Seq to simultaneously determine infection rate of all viruses and host responses in early summer, and found that 57% of examined plants were infected by TuMV, and a homologue of antiviral defence gene, ARGONAUTE 2 (AGO2), was upregulated in TuMV-infected plants." (PMID 31664159, 2020). "Moreover, we observed no obvious differences in Ago2-mediated RNA slicing by the endogenous miRNA-RISC isolated from Rag1−/− or Stat1/2−/− mice after either mock or NoVΔB2 infection." (PMID 32753500, 2020). "Second, given that enhanced accumulation of AGO2 transcript in TuMV-infected plants was not due to miR403 suppression, it may account for a transcriptional activation in response to the infection." (PMID 33230160, 2020). "Previous work with alphaviruses has shown the siRNA pathway to be antiviral, therefore it is not clear how increased expression of ago2 could lead to more efficient establishment of infection." (PMID 29772674, 2018). "However, the role of AGO2 in a bona fide PVX infection in N. benthamiana has not been studied, due to the lack of the appropriate mutant." (PMID 28432338, 2017). "Thus, both the lack of TuMV-AS9-GFP infection in single ago1 mutants and the lack of systemic infection of inflorescence in ago1–27 ago2–1 double mutants were not due to pleiotropic effects." (PMID 25806948, 2015). "Local TuMV-AS9-GFP infection foci were observed in inoculated rosette leaves, and virus was detected in noninoculated cauline leaves, from ago1–27 ago2–1 double mutant plants, but ago1–27 had no enhancing or suppressing effects when combined with ago2–1." (PMID 25806948, 2015). "To determine whether Ago2, Dicer-2 or TSN expression levels are modulated during DENV2 infection, we used quantitative real-time PCR to measure component mRNA levels in midguts at the initial site of infection." (PMID 21356105, 2011). "Though these differences may be due to several reasons, a likely possibility is that, whereas inactivation of AGO2 through CRISPR/Cas9 is complete, downregulation of DCL factors through RNAi is only partial and, thus, the remaining DCL amounts may still contribute to limit infection." (PMID 34623234, 2021). "With regard to the in vivo data, it is important to note that Tombusvirus-infected N. benthamiana plants were recently reported to show an increased accumulation of AGO2 at late infection stages (≥6 dpi), irrespective of whether the viruses expressed p19 or not." (PMID 29691336, 2018). "However, using RNA ChIP analyses we found that exosomes from HCV J6/JFH-1 infected Huh 7.5 cells and exosomes from the two patient groups that have active infection, treatment-naïve and treatment non-responders, showed increased proportion of miRNA-122 in complex with Ago2." (PMID 25275643, 2014). "Regardless of the multiplicity of infection (MOI) tested, virus replication was significantly reduced compared to eGFP-expressing control cells in the Ago2-expressing AF525 cells." (PMID 39984048, 2025). "The results showed that infection of NHBE and Calu-3 cells with SARS-CoV-2 did not impact mRNA expression levels of AGO2, DICER1, DGCR8, DROSHA, and XPO5 at 24 and 48 h post infection, in good concordance with our results on patient samples." (PMID 37243263, 2023). "For PMMoV infection, RefFinder identified the top four stable reference genes as RdR6, UBC, Tspan, and ACT while the least stable were AGO2, PGK, and L23, none of which were suitable as a reference gene." (PMID 36840204, 2023).